TNF (tumor necrosis factor)
Diseases named in the same sentence as TNF in open-access papers (continued):
Sharing a sentence is not in itself a finding about the gene and the disease.
endothelial dysfunction (continued). "Endothelial pathology is accompanied by excessive production of factors, called endothelial dysfunction markers, related to the inflammatory process, such as tumor necrosis factor—TNFα—or interleukin 6 (IL-6)." (PMID 30610442, 2019). "Together, this data provides evidence that endothelial GATA2 mRNA expression is reduced by inducing endothelial dysfunction, using either media rich in placental factors, or TNFα." (PMID 30659233, 2019). "Meanwhile, overexpression of miR-21 using agomir abolished DMY attenuated endothelial dysfunction in TNF-α treated HUVECs." (PMID 29682517, 2018). "Further, studies have demonstrated through administration of anti-TNF therapy, the role of TNF-α in endothelial dysfunction." (PMID 30572572, 2018). "Taken together, these findings demonstrated that miR-21 contributed to TNF-α-induced HUVECs dysfunction and the attenuating effects of DMY on endothelial dysfunction induced by TNF-α dependent on repressing miR-21 expression." (PMID 29682517, 2018). "Collectively, these results demonstrate that DMY attenuates TNF-α-induced endothelial dysfunction through mediating miR-21/DDAH1/ADMA cascade." (PMID 29682517, 2018). "The result of the present study demonstrated that DMY decreased both intracellular and extracellular ADMA concentration induced by TNF-α in a miR-21-dependant manner, resulting in attenuated endothelial dysfunction." (PMID 29682517, 2018). "Rabbits with experimentally induced hypercholesterolemia presented with elevated levels of TNF-α, IL-6, IL-1, and selected endothelial dysfunction markers, as it was seen in a rat model." (PMID 29713239, 2018). "The current conventional drugs for RA treatment, including glucocorticoids and etanercept (a TNF-α inhibitor), have been demonstrated to improve endothelial dysfunction through the anti-inflammatory effect in RA rat models." (PMID 30577824, 2018). "One of the important inflammatory mediators that contribute to RA joints arthritis of TNF-α, also proven to play a role in endothelial dysfunction and play a role in increasing intracellular lipolysis, thus increasing circulating FFA levels." (PMID 30123370, 2018). "Pro-inflammatory changes such as increased IL-6 and TNF-α levels are known to trigger acute phase protein responses and increase endothelins exhibiting signs similar to endothelial dysfunction." (PMID 30097052, 2018). "TNF-α was used to induce endothelial dysfunction in primary HUVECs and the expression of vascular cell adhesion molecule (VCAM-1; a marker of endothelial dysfunction) assessed." (PMID 29466360, 2018). "Compared with control or vehicle-treated control, TNF-α treatment resulted in a significant endothelial dysfunction as evidenced by decreased tube formation and migration; however, these insults were attenuated by treatment with DMY (25 μM, P < 0.01)." (PMID 29682517, 2018). "We used TNF-α to induce endothelial dysfunction in vitro, consistent with our previous studies we found that TNF-α significantly increased expression of VCAM and ET-1." (PMID 29641523, 2018). "TNFα is also involved in the early phase of the cytokine cascade in a pro-inflammatory state that promotes endothelial dysfunction and induction of pro-inflammatory genes including those of iNOS and COX2." (PMID 29483877, 2018). "Our group and others have used the pro-inflammatory cytokine TNF-α to model endothelial dysfunction in vitro with respect to preeclampsia." (PMID 29641523, 2018). "Arterial wall aging is also accelerated by up-regulation of TNF-α, firstly for a direct effect as seen on human coronary arteries and secondly by an indirect effect due to its pro-inflammatory and pro-endothelial dysfunction ability." (PMID 29415476, 2018). "There is also evidence to suggest that endothelial dysfunction is influenced by other inflammatory cytokines in addition to TNF." (PMID 29855349, 2018).
endothelial dysfunction (continued). "In contrast, DMY or blockade of miR-21 expression ameliorated endothelial dysfunction in HUVECs treated with TNF-α through downregulation of miR-21 expression, whereas these effects were abolished by overexpression of miR-21." (PMID 29682517, 2018). "TNF-α is thought to be the major cytokine contributing to endothelial dysfunction, leading to inflammatory activation." (PMID 30400570, 2018). "Increases of inflammatory cytokines TNFα and interleukin-6 were reported in regard to endothelial damage and are considered features of both endothelial dysfunction and early stages of plaque formation." (PMID 29615651, 2018). "Etanercept, a tumor necrosis factor-α (TNF-α) inhibitor, was demonstrated to attenuate endothelial dysfunction in a rat model." (PMID 30577824, 2018). "TNF-inhibitors are effective treatments for joint inflammation in RA; however, very little is known about their effect on atherosclerosis and endothelial dysfunction, which occur in this disease." (PMID 30526655, 2018). "The two inflammatory markers TNFα and IL-6, and the endothelial dysfunction marker ET-1 showed a significant difference in the two groups, p < 0.05." (PMID 28925931, 2017). "To this aim, we induced endothelial dysfunction (ED) by activating HUVECs with TNF-α or IL-1β and measured the impact of RES in these cells." (PMID 28610607, 2017). "TNFα also increases the production of reactive oxygen species (ROS), perpetuating endothelial dysfunction." (PMID 28059114, 2017). "We found that BACE1 upregulation in TNFα-treated endothelial cells leads to ST6Gal-I proteolysis and results in endothelial dysfunction and monocyte-endothelial cell adhesion." (PMID 28091531, 2017). "We therefore measured the circulating levels of the main pro-inflammatory mediators that can be directly affected by Mg/Ca and by endothelial dysfunction, including TNF-α, IL-6 and CRP: they were all substantially higher in AAD patients than controls." (PMID 28070203, 2017). "The interaction of TNF-α and IL-6 appears to have a pivotal role in T2D-induced endothelial dysfunction in coronary microcirculation." (PMID 29095915, 2017). "Elevated plasma CRP, TNF-α and IL-6 levels can induce endothelial dysfunction by enhancing free radical generation and simultaneously reducing endothelial nitric oxide (eNO) generation and its half-life." (PMID 28824543, 2017). "The results suggest significant protective effects of rbFGF (10 ng/mL), similar to LSM against TNF-α-induced endothelial dysfunction." (PMID 29354066, 2017). "Previously, we reported that TNF-α has a crucial role in endothelial dysfunction in T2D by activating the glycation end (AGE) product/receptor of AGE (RAGE) and the nuclear factor-kB (NF-kB) signaling pathway." (PMID 29095915, 2017). "Further, elimination of either IL-6 or TNF-α restored the impaired redox balance between the levels of ROS and the antioxidant directly responsible for endothelial dysfunction." (PMID 29095915, 2017). "To further investigate the molecular mechanism responsible for TMAO-induced endothelial dysfunction in aging, we measured expression of pro-inflammatory cytokines TNF-α, IL-1β, activity of eNOS, and levels of superoxide production in the aorta." (PMID 28611682, 2017). "The key role of TNF-α in mediating the detrimental effects of inflammation on endothelial dysfunction and vascular homeostasis is also supported by the results of animal and human studies investigating the effects of specific TNF-α inhibitors." (PMID 29430085, 2017). "In our study, NPY, CA, AngII, ET-1, CRP, IL-6, and TNF-α increased while MT decreased after SD, which is characteristic of the beginning of myocardial injury due to hormone disorders, inflammation, and endothelial dysfunction." (PMID 28479928, 2017). "Inflammatory biomarkers (Il-6 and TNFα) and an endothelial dysfunction biomarker (ET-1) showed significantly higher levels in T2DM-CKD, and a positive correlation with TMAO in the T2DM-CKD patients." (PMID 28925931, 2017).
endothelial dysfunction (continued). "In this study, we demonstrated that LSM derived from a new LSS system had unexpected protective effects in TNF-α-induced endothelial dysfunction [reactive oxygen species (ROS) induction, inflammation, and thrombosis]." (PMID 29354066, 2017). "Evaluation of the protective effects of LSM and SM on endothelial dysfunction induced by tumor necrosis factor (TNF)-α (10 ng/mL), which leads to production of reactive oxygen species (ROS), inflammatory monocyte adhesion, and tissue factor activity." (PMID 29354066, 2017). "Using the modified cone-and-plate shear device, we also found that LSM was effective in rescuing cells from TNF-α-induced endothelial dysfunction." (PMID 29354066, 2017). "Inflammatory response acts in endothelial dysfunction appearance by means of proinflammatory cytokines, such as TNF-α, IL-6, and IL-1." (PMID 29200598, 2017). "Endothelial dysfunction was induced in HUVECs using TNFα, increasing expression of cell adhesion molecule VCAM1 and adhesion of peripheral blood mononuclear cells, both of which were increased further by resveratrol." (PMID 28500309, 2017). "Of note, cigarette use induces endothelial dysfunction and increased circulating levels of inflammatory cytokines such as TNF-α, a cytokine which has been detected in the circulation of smokers and COPD patients." (PMID 29326688, 2017). "To investigate the role of macrophage TNFα in nicotine induction of endothelial dysfunction in obese rats, we examined the effects of macrophage conditioned medium on eNOS and NADPH oxidase subunits gp91phox and p22phox in HUVECs." (PMID 29236702, 2017). "Tumor necrosis factor α (TNFα) is a major pro-inflammatory cytokine that contributes to endothelial dysfunction through dysregulation and uncoupling of eNOS." (PMID 28245243, 2017). "Despite such a significant contribution of IL-6 and TNF-α to endothelial dysfunction a knowledge gap investigating how IL-6 and TNF-α affect each other in endothelial cell in T2D still exists." (PMID 29095915, 2017). "Previous studies proposed that one of the mechanisms by which AGE/RAGE contributes to endothelial dysfunction is through regulation of the production and expression of tumor necrosis factor (TNF)-α." (PMID 29259621, 2017). "It implicates that IL-6 and TNF-α are interactive each other to determine the endothelial dysfunction in type 2 diabetic coronary arterioles, but a further study is needed to confirm its direct relationship." (PMID 29095915, 2017). "It appears to be the first study to find that a reciprocal inhibitory regulation between TNF-α and IL-6 is responsible for endothelial dysfunction in T2D." (PMID 29095915, 2017). "Urinary TNF-alpha is significantly elevated in obese adolescents and correlates with urinary ET-1, which is recognized as a biomarker for endothelial dysfunction." (PMID 28344817, 2017). "Our results demonstrate that CO restores TNF-α-induced eNOS downregulation and endothelial dysfunction by suppressing NF-κB-responsive miR-155-5p biogenesis." (PMID 29170479, 2017). "The pro-inflammatory cytokine TNF-α is a crucial regulator in insulin resistance and endothelial dysfunction in T2D." (PMID 29095915, 2017). "Recent studies suggested that, although found to function in the activation of MAPK/p38, thrombospondin-1, together with TNF-α, played critical roles in micro-endothelial dysfunction, such as increasing apoptosis and limiting angiogenesis." (PMID 29152123, 2017). "By contrast, anti-TNFα treatment suppresses several markers of endothelial dysfunction including oxidative stress, pro-apoptotic markers and pro-inflammatory gene expression including iNOS." (PMID 28932625, 2016). "In this regard, several TNFα inhibitors including etanercept and infliximab have been demonstrated to inhibit intravascular TNFα and reverse endothelial dysfunction." (PMID 28932625, 2016).
endothelial dysfunction (continued). "During the last decade, the proinflammatory cytokines TNF-α and IL-1β have emerged as biomarkers and mediators of oxidative stress and endothelial dysfunction in several cardiovascular diseases." (PMID 27894297, 2016). "To this aim, we induced endothelial dysfunction (ED) by activating HUVECs with TNF-α and measured the impact of TAE on parameters of ED." (PMID 26840280, 2016). "TNF-α was also shown to stimulate endothelial microparticles (EMPs) releasing, which is a marker of endothelial dysfunction, and reactive oxygen species (ROS) production, which suggest that ROS are important mediators of TNF pathway." (PMID 26504819, 2015). "TNF-α, another inflammatory cytokine that can impair NO activity in endothelial cells by promoting oxidative stress (another aspect of endothelial dysfunction), has been found to be induced in bone marrow cells by TSH." (PMID 25452768, 2015). "It has been reported that apigenin inhibits the uptake of OxLDL and OxLDL induced endothelial dysfunction and attenuates the secretion of nitric oxide and tumor necrosis factor-α." (PMID 25960827, 2015). "AV leaflets cultured in TNFα for 21 days showed significant endothelial dysfunction, with decreases in CD31, VE-cadherin, and eNOS on both the fibrosa and the ventricularis." (PMID 25874717, 2015). "Under the conditions of endothelial dysfunction, cytokines, and vasoactive peptides, including tumor necrosis factor α (TNF-α), and Ang II induce a variety of adhesion molecules." (PMID 25710020, 2015). "We decided to study the effect of several cytokines involved in the inflammatory process, such as TNF-α, IL-6 and IL-1β on some markers of endothelial dysfunction and activation in ECs and the possible protective effect of the oleate against those stimuli." (PMID 26055507, 2015). "The increased inflammatory cytokines, IL-1β, IL-6, and TNF-α, under diabetic conditions promote the progression of endothelial dysfunctions, neutrophil accumulation, and coagulation." (PMID 26633490, 2015). "Others have found that liraglutide inhibits high-glucose induced endoplasmic reticulum stress, and also TNFα induced markers of endothelial dysfunction such as PAI-1, ICAM-1, and VCAM-1 in human umbilical vein endothelial cells (HUVECs)." (PMID 24835252, 2014). "Decreased nitric oxide (NO) bioavailability appears to be a common and critical step linking TNF-α to endothelial dysfunction." (PMID 24968272, 2014). "Anti-TNF-α agents have also been shown to reduce levels of plasma biomarkers of endothelial dysfunction, although results have been inconsistent." (PMID 24968272, 2014). "In our study, this is consistent with the observed significant decrease in TNFα production and leukocyte superoxide anion production, which are known mediators of endothelial dysfunction." (PMID 25497775, 2014). "The effect of TNF-α on NO availability and subsequent endothelial dysfunction has also been demonstrated in vivo in both animal and human models." (PMID 24968272, 2014). "The concentration of 5 ng/ml TNF-α was selected as an in vitro endothelial dysfunction model, and GXSTC increased the level of NO in a dose-dependent manner in TNF-α-stimulated ECV304 cells." (PMID 25120637, 2014). "On the other hand, pro-inflammatory cytokines, such as TNF-α, induce endothelial dysfunction in animal models and humans." (PMID 25518980, 2014). "The inhibition of tectorigenin on TNF-α and IL-6 production was, at least in part, responsible for its amelioration of endothelial dysfunction." (PMID 23840461, 2013). "TNF-α, one of the most important proinflammatory cytokines, is well known to increase ROS production in the endothelium and subsequently induce endothelial dysfunction." (PMID 24396568, 2013). "In conclusion, p66Shc acts as a novel intermediate in the TNFα pathway mediating endothelial dysfunction, and its action requires JNK-dependent phosphorylation of p66Shc on Ser36." (PMID 24349153, 2013).
endothelial dysfunction (continued). "In a former study of our group, we demonstrated that in long-term anti-TNF-α infliximab-treated RA patients, the intravenous infusion of this monoclonal antibody yielded a significant rapid but transient improvement of endothelial dysfunction." (PMID 22899879, 2012). "Generally speaking, the accumulation of visceral fat due to metabolic syndrome will lead to over-expression of adipokines, such as resistin, IL-6, and TNF-α, resulting in diminish eNOS activity, less NO generation and endothelial dysfunction." (PMID 23029112, 2012). "In particular, visceral fat contributes to inflammation and endothelial dysfunction through secretion of adipokines, like TNFα or IL-6, which are secreted by the lipid tissue after macrophage recruitment (through monocyte chemoattractant protein-1 (MCP-1)." (PMID 21808640, 2011). "TNF-α is one of the mediators of endothelial dysfunction through the activation of transcription factors, including NF-κB." (PMID 21754991, 2011). "Taken together these data suggest the potential use of this NF-κB gene signature in analyzing the role of TNF-α in the endothelial dysfunction, as well as in breast tumors independently of the presence of ERα." (PMID 21754991, 2011). "For example, Tian-Lun Yang has reported that FF reduces serum TNF-α levels of rats with LDL-induced endothelial dysfunction." (PMID 21234421, 2010). "TNFα is one of the major proinflammatory cytokines that is dysregulated in inflammatory diseases mentioned earlier and has been shown to contribute to endothelial dysfunction." (PMID 18691416, 2008). "In humans, neutralizing TNFα using an anti-TNFα monoclonal antibody corrects endothelial dysfunction observed in chronic inflammatory diseases, such as RA and systemic vasculitis." (PMID 17335569, 2007). "Gene expression of MMP-2 and MMP-9 in peripheral blood leukocytes and circulating levels of MMP-2, MMP-9, pro-inflammatory cytokines (TNF-α, IL-6), and endothelial dysfunction markers (Endothelin-1 [ET-1], adhesion molecules) were quantified via qRT-PCR and ELISA." (PMID 41598609, 2026). "Similarly, TNF-α contributes to endothelial dysfunction, increased vascular stiffness, and impaired insulin signaling." (PMID 41602164, 2026). "Following acute or repetitive ischemic episodes, persistent immune activation-mediated through interleukin-6 (IL-6), interleukin-1β (IL-1β), and tumor necrosis factor-α (TNF-α)-promotes endothelial dysfunction, microvascular instability, and extracellular matrix remodeling." (PMID 42195345, 2026). "Shared mechanisms include visceral adiposity, adipokine imbalance, insulin resistance, systemic cytokine activation (IL-6, TNF-α), endothelial dysfunction, oxidative stress, intermittent hypoxia, and profibrotic transforming growth factor-beta (TGF-β)–mediated pathways." (PMID 41995935, 2026). "Additionally, TNF-α contributes to endothelial dysfunction by promoting oxidative stress, inflammation, and apoptosis within the vasculature [1227, 1228]." (PMID 40407975, 2025). "LOX exacerbates vascular inflammation and endothelial dysfunction by activating the nuclear factor-κB (NF-κB) pathway, culminating in the secretion of pro-inflammatory cytokines, including interleukin-6 (IL-6) and tumor necrosis factor-α (TNF-α)." (PMID 40661776, 2025). "The resulting EC damage leads to an imbalance between vasodilation and vasoconstriction processes, reactive oxygen species (ROS) formation and cytokine release (IL-1, IL-6, TNF-alpha), decreased NO availability and finally endothelial dysfunction and thrombosis." (PMID 41155474, 2025). "GERD‐induced vagal nerve activity may influence blood pressure control, while inflammation, driven by cytokines such as IL‐6 and TNF‐α, promotes endothelial dysfunction, a precursor to HTN." (PMID 40225100, 2025).